KCNG2 (potassium voltage-gated channel modifier subfamily G member 2)
Description:
Modulates channel activity by shifting the threshold and the half-maximal activation to more negative values (Probable). Potassium channel subunit that does not form functional channels by itself (Probable).
Synonyms: KCNF2; Kv6.2
Tractability: Small molecule: an approved drug acts on it; it belongs to a druggable protein family. Antibody: its Gene Ontology location is reachable by antibodies, with high confidence; UniProt places it where antibodies can reach, with medium confidence; UniProt predicts a signal peptide or a membrane-spanning region.
Gene: Protein-coding gene on chromosome 18 (79,797,904 to 79,900,184, forward strand). Ensembl gene ENSG00000178342.
Subcellular location: Cell membrane
Pathways (Reactome):
Metabolism: Glucagon-like Peptide-1 (GLP1) regulates insulin secretion
Neuronal System: Voltage gated Potassium channels
Gene Ontology:
Molecular function: potassium channel regulator activity; monoatomic ion channel activity; voltage-gated potassium channel activity
Biological process: action potential; potassium ion transmembrane transport; monoatomic ion transport; potassium ion transport; protein homooligomerization; regulation of potassium ion transport; transmembrane transport
Cellular component: extracellular exosome; membrane; plasma membrane; voltage-gated potassium channel complex
Genetic constraint (gnomAD): Loss-of-function variants: 7 observed, 4.48 expected, observed/expected ratio (o/e) 1.56, 90% interval 0.82 to 1.94. That is too few expected variants to judge how well the gene tolerates losing a copy. Missense variants: 703 observed, 543.15 expected, observed/expected ratio (o/e) 1.29, 90% interval 1.22 to 1.38. Synonymous variants: 414 observed, 270.13 expected, observed/expected ratio (o/e) 1.53, 90% interval 1.41 to 1.66.
Homologues: Orthologues: chimpanzee KCNG2 (99% identical), macaque KCNG2 (97% identical), pig KCNG2 (92% identical), rat Kcng2 (89% identical), mouse Kcng2 (88% identical), tropical clawed frog kcng2 (61% identical), zebrafish kcng2 (60% identical). Paralogues in human: KCNG1 (56% identical), KCNG4 (55% identical), KCNG3 (38% identical), KCNB2 (35% identical), KCNS1 (33% identical), KCNV1 (31% identical), KCNS3 (30% identical), KCNC3 (30% identical), KCND1 (30% identical), KCNC1 (30% identical), KCNC4 (29% identical), and 19 more.
Diseases named in the same sentence as KCNG2 in open-access papers:
KCNG2 is named in the same sentence as 9 diseases in open-access papers, as found by Europe PMC text mining. Sharing a sentence is not in itself a finding about the gene and the disease. The quoted sentences say what the papers report.
epilepsy (1 paper, 2019). A brain disorder characterized by episodes of abnormally increased neuronal discharge resulting in transient episodes of sensory or motor neurological dysfunction, or psychic dysfunction.
glioma (1 paper, 2013). A benign or malignant brain and spinal cord tumor that arises from glial cells (astrocytes, oligodendrocytes, ependymal cells). "Our results indicate that alterations of eight out of eleven identified genes might have an important role in pathogenesis of glial tumors, while detected changes in GP2, KCNG2 and KIR3DL3 should be considered as passenger mutations, since these genes are not expressed in glial cells." (PMID 24358143, 2013).
Lassa fever (1 paper, 2021). A viral hemorrhagic fever that is caused by the Lassa virus, which is transmitted by contact with infected rodents; it is characterized by fever, headache, malaise, myalgia, and hearing loss. "Indeed, we identified several genes for which the expression correlated with infectious status, such as NFE2, PTP4A3, KCNG2, and a substantial number of genes for which the expression is associated with Lassa fever outcome." (PMID 33398113, 2021).
metabolic syndrome (1 paper, 2025). A cluster of metabolic risk factors for CARDIOVASCULAR DISEASES and TYPE 2 DIABETES MELLITUS. "Of the 22 female-specific MDD/metabolic syndrome pleiotropic regions, possible causal risk loci mapped to multiple genes (GPC6, SHISA9, RP11-154H12.3, KCNG2, TXNL4A, RBFA and ADNP2)." (PMID 40858613, 2025).
KCNG2 also shares sentences with these, for which no sentence is quoted: Arrhythmia (1 paper); opioid dependence (1); opioid use disorder (1); osteosarcoma (1); schizophrenia (1).